SLC30A1 (solute carrier family 30 member 1)
Diseases named in the same sentence as SLC30A1 in open-access papers (continued):
Sharing a sentence is not in itself a finding about the gene and the disease.
type 1 diabetes (1 paper, 2013). "This marker tags the zinc transporter SLC30A1 and zinc transport has an established role in type 1 diabetes, yet this gene was only identified as a susceptibility locus by 2D-MCP." (PMID 23825936, 2013).
cancer (16 papers, 2016 to 2025). A tumor composed of atypical neoplastic, often pleomorphic cells that invade other tissues. "Loss of function by mutations in SLC30A1 may reduce intracellular zinc levels and contribute to cancer progression." (PMID 40362545, 2025). "Furthermore, altered expression levels of SLC30A1 have been linked to Alzheimer's disease and different types of cancers." (PMID 33996761, 2021). "To further explore whether the SLC30 family genes could exert oncogenic or tumor-suppressive effects through cancer-related pathways, we used the GSCALite platform to investigate the regulatory effects of the SLC30A1-10 genes on common cancer pathways." (PMID 35154468, 2022). "Therefore, cancer cells may activate MTF1 in the presence of high concentrations of this metal, causing an underexpression of SLC39A10 and an overexpression of SLC30A1 in order to recover zinc homeostasis." (PMID 40176904, 2025). "Furthermore, functions of these transcription factors were mainly enriched in regulatory RNA transcription, suggesting that SLC30A1/10 may have the ability to participate in the regulation of invasion and metastasis at the transcriptional level in cancers." (PMID 35154468, 2022). "The membrane transporter ABCC1 (MRP1), which confers multidrug resistance to cancer cells, was also enriched in the Panc-1 library, along with three other SLC transporters, SLC4A2, SLC30A1, and SLC12A7 (KCC4), plus the epidermal growth factor receptor EGFR and lipid transport protein ESYT2." (PMID 37295717, 2023). "In addition, the results showed that the high expression of SLC30A1 was resistant to 79 drugs or small molecules; Two drugs (Neopeltolide and Tozasertib) can inhibit the high expression of SLC30A10 in cancers." (PMID 35154468, 2022). "Finally, we evaluated the correlation between SLC30A1/10 expression and the IC50 of Cancer Drug Sensitivity Genomics (GDSC)." (PMID 35154468, 2022). "In addition, the results showed that high expression of SLC30A1 was resistant to 79 drugs; two drugs (Neopeltolide and Tozasertib) can inhibit the high expression of SLC30A10 in cancers." (PMID 35154468, 2022). "In a scRNA-seq study involving 10 pairs of human cancer and adjacent normal tissue, a distinct subset of TAMs characterized by high expression of metallothionein family genes, particularly zinc transporter genes SLC30A1 (ZNT-1) and SLC39A8 (ZIP-8), was identified." (PMID 37746302, 2023).
tumor (12 papers, 2015 to 2025). "Meanwhile, SLC30A1-7, and 9 were significantly correlated with advanced tumor stage and nodal metastasis status, SLC30A5-7, and 9–10 were significantly related to the Helicobacter pylori infection status of GC patients." (PMID 33110097, 2020). "Although no tumor was found in animals (n = 5) injected with cells transfected with vector, all animals injected with cells expressing SLC30A1 (n = 5) or SERPINB2 (n = 4) developed tumor at the xenograft site within 4 weeks after injection." (PMID 26338969, 2015). "For tumor stages, SLC30A1, SLC30A7 and SLC30A10 groups significantly varied." (PMID 35154468, 2022). "Moreover, assessment of the correlation between SLC30A family genes expression levels and the tumor stages of GC patients indicated that the expression levels of most SLC30A family genes, including SLC30A1, 5–7, and 9, were significantly and positively associated with tumor stage in GC patients." (PMID 33110097, 2020). "The differential expression of SLC30A1, SLC30A5, SLC30A6, SLC30A9 and SLC30A10 was found to vary with tumor stage and grade and appears to be related mostly to early events in PCa development and progression." (PMID 27833104, 2016).
infection (9 papers, 2011 to 2024). The state of being infected such as from the introduction of a foreign agent such as serum, vaccine, antigenic substance or organism. "We instead observed a reduced infection of SLC30A1-deficient cells compared to wild type cells in multicycle infections." (PMID 31320712, 2019). "This is consistent with the reduced amount of viral RNA in the SLC30A1-deficient cells at the later stages of the infection (>4 hours), when reinfection by the produced viral particles starts to occur." (PMID 31320712, 2019). "Interestingly, SLC30A1-deficient cells produced significantly reduced titers of virus particles after infection, likely due to a defect at the late stage of the virus cycle, which could become relevant in a multicycle study." (PMID 31320712, 2019). "Given that the spleen is the largest secondary lymphoid organ and is a major source of bacterial burden during systemic infection, we dissected the spleen 4 hr after infection and examined Slc30a1-flag expression in splenic macrophages." (PMID 39475776, 2024). "At the same time, zebrafish respond to the infection by activating the expression of the Zn transporters Slc30a1 and Slc30a4, whose mammalian homologs mediate a redistribution of Zn in phagocytes aimed at intoxicating bacteria with a metal excess." (PMID 36674459, 2023). "Genetic screens with the cytolytic vesicular stomatitis virus (VSV) showed that the loss of two SLCs genes, encoding the sialic acid transporter SLC35A1/CST and the zinc transporter SLC30A1/ZnT1, affected cell survival upon infection." (PMID 31320712, 2019). "Despite evidence suggesting a link between zinc regulators and macrophage function, whether and how Slc30a1 regulates macrophage function during infection remains poorly understood." (PMID 39475776, 2024). "To validate this in vitro finding in vivo, we gave C57BL/6 mice an intraperitoneal (i.p.)injection of a sublethal dose of attenuated Salmonella (1 × 105 CFU per mouse); at 4 hr post-infection (4 hpi), Slc30a1 expression was significantly higher in peritoneal macrophages compared to uninfected mice." (PMID 39475776, 2024). "We also quantified Salmonella burden at 4, 24, and 48 hpi and found significantly higher numbers of bacterial cells in the peritoneal cavity, blood, spleen, and liver of infected Slc30a1 cKO mice compared to control mice, particularly at 24 hpi, indicating severe systemic infection." (PMID 39475776, 2024). "Expression of MTs and slc30a1 (ZnT1) in MTF-1KD cells was evaluated under basal conditions and upon infection with L.V." (PMID 38239429, 2023).
immune diseases (1 paper, 2022). "Our results validated that the SLC30A1/10 was associated with the pathogenesis of immune diseases and many solid cancers." (PMID 35154468, 2022).
SLC30A1 also shares sentences with these, for which no sentence is quoted: Zinc deficiency (15 papers); Obesity (5); Alzheimer disease (3); acrodermatitis enteropathica (2); atrial fibrillation (2); epidermodysplasia verruciformis (2); esophageal cancer (2); mild cognitive impairment (2); primary aldosteronism (2); thyroid cancer (2); adenocarcinoma (1); adenoma (1); amyotrophic lateral sclerosis (1); brain glioma (1); Cirrhosis (1); colon adenocarcinoma (1); Crohn disease (1); dementia (1); ductal adenocarcinoma (1); Ehlers-Danlos syndrome (1); gastric tumor (1); glioblastoma (1); heart malformations (1); inflammation (1); lymph node metastasis (1); mastitis (1); melanoma (1); neuroblastoma (1); neurodegenerative disease (1); pancreatic adenocarcinoma (1).
A further 14 diseases each share a sentence with SLC30A1 in 1 paper.